NOTCH1 (notch receptor 1)
Diseases named in the same sentence as NOTCH1 in open-access papers (continued):
Sharing a sentence is not in itself a finding about the gene and the disease.
dilation (3 papers, 2015 to 2024). "Furthermore, BAV has been significantly associated with rare but highly penetrant exonal mutations in the NOTCH1 gene, and BAV presenting together with ascending aortic dilation has been also demonstrated to be significantly associated with other rare variants in the NOTCH1 gene." (PMID 29854087, 2018). "Furthermore, examination of the proximal aorta of Notch1+/−; Nos3−/− mice reveals elastic fiber degradation, a trend toward increased matrix metalloproteinase 2 expression, and increased smooth muscle cell apoptosis, features characteristic of aneurysmal disease." (PMID 25914885, 2015).
dysplasia (3 papers, 2018 to 2025). A usually neoplastic transformation of the cell, associated with altered architectural tissue patterns. "While 100% of 10-week old VN-/- mice showed low-grade dysplasia, 30% of 30-week old VN-/- mice developed high-grade dysplasia in addition to the low-grade dysplasia, suggesting that loss of epithelial cell-intrinsic Notch-1 promotes tumorigenesis." (PMID 30323897, 2018). "In summary, this section identifies SNHG1 as a clinically and mechanistically relevant lncRNA that modulates the interaction between ULK1 and Notch1, and is significantly upregulated in BE patients who later developed dysplasia." (PMID 40629071, 2025). "Decreases in Notch-1 expression are known to lead to defects in the mucosal barrier and IEC differentiation and function, but the mechanism of how this leads to the development of dysplasia is not fully understood." (PMID 30323897, 2018).
esophageal adenocarcinoma (3 papers, 2014 to 2025). A malignant tumor with glandular differentiation arising predominantly from Barrett mucosa in the lower third of the esophagus. "Because Smad3 was recently shown to interact with Notch1 in esophageal adenocarcinoma cells after treatment with TGF-β, we tested if N1ICD binding to the Sox9 promoter RBP-Jκ site was dependent on TGF-β signaling in lung ADC." (PMID 25004243, 2014). "Collectively, these results establish the novel involvement of Notch1 signaling in mediating EMT induced by acidic bile salts in BE, addressing an important gap in understanding Barrett’s esophagus progression and providing potential new avenues for therapeutic intervention." (PMID 40629071, 2025).
experimental autoimmune encephalomyelitis (3 papers, 2016 to 2021). An autoimmune demyelinating disease of the central nervous system that is produced experimentally in animals by the injection of homogenized brain or spinal cord in Freund's adjuvant. "The blockade of Notch1 signaling by γ-secretase inhibitor resulted in the marked downregulation of Th17 cells, effective cytokine IL-17 secretion, and Th17-mediated disease progression in experimental autoimmune encephalomyelitis (EAE)." (PMID 29686529, 2018).
gynecologic cancer (3 papers, 2022 to 2024). "NOTCH1 variants were called in a retrospective study conducted in 299 gynecological cancers identifying somatic mutations in the clear cell carcinoma subtype." (PMID 36010253, 2022). "While contributions of Notch1 in gynecologic cancer and cancer stem cells have been described previously, other stemness-associated pathways such as Wnt signaling could not be ruled out." (PMID 38438589, 2024).
hemangioma (3 papers, 2011 to 2022). A benign vascular lesion characterized by the formation of capillary-sized or cavernous vascular channels. "Both inhibited the expression of the endothelial differentiation markers CD31, VE-cadherin, and the expression of the hemangioma endothelial markers NOTCH1, VEGFR1, and plexin D1 compared with the DMSO control (for P values)." (PMID 34874911, 2022). "Endothelial differentiation markers, CD31 and CDH5 and hemangioma endothelial markers NOTCH1, PLXND1 and VEGFR1 under each treatment condition in four biological replicates, determined by qPCR, were standardized as described." (PMID 31358114, 2019).
hematoma (3 papers, 2016 to 2022). A hematoma is a collection of blood from a vascular structure into an extravascular space. "Consistent with transcriptomic analysis results, Notch1 protein expression was decreased by ~ 60% in the striatum around the hematoma lesion in the ICH group compared with the vehicle group." (PMID 36028880, 2022). "First, results showed elevated levels of Botch and Notch1-TMIC in brain tissue around hematoma after ICH and cultured neuron exposed to OxyHb, while Notch1-FL was only detected in sham group." (PMID 29221132, 2017). "At the same time, Notch-1 and NeuN were co-expressed in neurons of hematoma-surrounding tissues." (PMID 27655677, 2016). "Our findings revealed that Notch-1 and JNK increased in hematoma-surrounding neurons tissues following ICH during ischemic conditions (all p<0.05)." (PMID 27655677, 2016).
Hepatic steatosis (3 papers, 2016 to 2025). Steatosis is a term used to denote lipid accumulation within hepatocytes. "Taken together, these results suggest that Notch1 signaling is essential for the Foxo1-mediated regulation of hepatic steatosis, inflammation, and fibrosis in macrophages during NASH progression." (PMID 39122845, 2024). "Lower serum triacylglycerol levels in NAS mice fed a HFD further suggest that Notch1 inhibition prevents hepatic steatosis." (PMID 26786165, 2016).
intervertebral disc degeneration (3 papers, 2022 to 2025). "HOTAIR/miR-34a-5p/Notch1 signaling pathway may regulate the development of intervertebral disc degeneration." (PMID 35626352, 2022).
intestinal cancer (3 papers, 2019 to 2024). "Therefore, KPN tumors represent models of MSS serrated intestinal cancer in which NOTCH1 signaling drives metastasis without impacting tumor initiation." (PMID 31526760, 2019).
ischemic disease (3 papers, 2018 to 2025). Lack of blood supply to an area of the body, resulting in impairment of tissue oxygenation. "Due to its overexpression, c-Notch1 (Notch homolog 1, translocation-associated) levels and its downstream signaling pathways are enhanced, suggesting that CatK could contribute to Notch1-dependent neovascularization and be a potential therapeutic target for ischemic disease." (PMID 36430239, 2022).
kidney cancer (3 papers, 2012 to 2016). Primary or metastatic malignant neoplasm involving the kidney. "To this end, we determined the correlation in the expression of PlexinD1 with Notch1 and Notch3 in datasets of prostate, colon, thyroid and kidney cancers." (PMID 27749937, 2016). "Although Notch1 has been reported to be pro-metastatic in multiple cancers, the exact role of Notch signaling in kidney cancer is not clear yet, so we intended to explore the function of Notch signaling in the metastasis of ccRCC." (PMID 22506064, 2012).
leprosy (3 papers, 2018 to 2024). Leprosy is a chronic infectious disease affecting primarily the skin and peripheral nervous system. "Therefore, the aim of this study was to establish the relationship between the expression of components of the Notch signaling pathway (Hes-1, Hey-1, Runx-1, Jagged-1, Notch-1, and Numb) with tissue changes in the skin and dermal nerve fibers of leprosy patients." (PMID 32265900, 2020). "Furthermore, NOTCH1/2 are expressed on activated Th1 cells and are critical to the protective response against Leishmania major infection by the production of IFN-γ, which is also important for leprosy protection by JAG1 stimulation." (PMID 29593724, 2018).
Lewis lung carcinoma (3 papers, 2017 to 2025). "CRTC1/Notch1-dysregulated Lewis lung carcinoma (LLC) cells were co-cultured with T cells to evaluate T cell activation and function." (PMID 40977688, 2025). "In intracellular Notch1-expressing mice, an increase in cytotoxicity of CD8+ T cells mediated by IFN-γ and granzyme B production was observed, which delayed tumor growth in the syngeneic murine Lewis lung carcinoma model." (PMID 39209451, 2024).
lymphedema (3 papers, 2021 to 2025). Excess fluid collection in tissues, causing swelling. "Seven out of 235 probands, five with sporadic and two with familial lymphedema, were found to carry rare missense variants in the NOTCH1 gene." (PMID 33247628, 2021). "Out of 235 lymphedema patients tested for variants in NOTCH1, seven were found to carry rare variants in this gene." (PMID 33247628, 2021). "Seven out of 235 probands, five with sporadic and two with familial lymphedema, were found to carry rare missense variants in the NOTCH1 gene.Conclusions: Our results propose that NOTCH1 could be a novel candidate for genetic predisposition to lymphedema." (PMID 33247628, 2021). "Our results propose that NOTCH1 could be a novel candidate for genetic predisposition to lymphedema." (PMID 33247628, 2021). "Upregulation of Notch1 signaling ameliorates VEGFR3 deficiency and can be used as a potential therapeutic approach for treating lymphedema." (PMID 40766782, 2025). "The aim of the study was to define the genotype of these patients, in order to explore the role of the candidate gene NOTCH1 in lymphedema.We studied lymphatic malformations related to NOTCH1 variants." (PMID 33247628, 2021). "In addition, Notch1 knockout mice are insensitive to the therapeutic effects of LTB4 antagonists, which further supports the important role of Notch1 signaling in LTB4 regulation of lymphedema." (PMID 40766782, 2025). "In conclusion, the Notch1 signaling pathway can be targeted for the treatment of lymphedema." (PMID 40766782, 2025). "The development of drugs related to the Notch1 signaling pathway may be beneficial for the treatment of lymphedema." (PMID 40766782, 2025). "Notch1 signaling may play an important role in the prevention or treatment of acquired lymphedema." (PMID 40766782, 2025). "Interestingly, whether Notch1 signaling is downregulated or upregulated in the treatment of lymphedema, which may result from differences in Notch1 upstream signaling, remains a question worth exploring." (PMID 40766782, 2025). "In the first step, we analyzed genes known to be linked to lymphedema: 235 out of 246 patients tested negative for the most frequent variants and underwent testing for variants in a group of candidate genes, including the NOTCH1 gene, selected from the database of mouse models." (PMID 33247628, 2021).
MALT lymphoma (3 papers, 2020 to 2021). An indolent, extranodal type of non-Hodgkin lymphoma composed of small B-lymphocytes (centrocyte-like cells). "NOTCH1/2 mutations have been associated to aggressive course in some lymphoproliferative disorders, but the prognostic impact in MALT lymphomas remains to be determined." (PMID 35008340, 2021). "Recurrent mutations have been described in NOTCH1 and NOTCH2, but mainly in MALT lymphomas of the ocular adnexa (8–10%) and dura (29%)." (PMID 35008340, 2021). "NOTCH1 mutations occur in 5% of SMZLs, but at a much lower frequency in NMZLs and not at all MALT lymphomas." (PMID 34590593, 2021). "In a study of gastric MALT lymphoma, NOTCH1 mutations were enriched in patients who failed to H. pylori eradication." (PMID 35008340, 2021). "In fact, Mensah and collaborators examined the mutational status of PEST domain in 23 cases of MALT lymphomas and no alterations were found, although in a further study, mutations in Notch 1 and Notch 2 were found in 8% of analyzed cases." (PMID 33374160, 2020).
Marfan syndrome (3 papers, 2019 to 2022). A disorder of the connective tissue. "Also NOTCH1 levels were increased in Marfan syndrome samples, however they were similar to control samples in BAV and TAV samples." (PMID 31434939, 2019). "Considering the role of PDE5 in regulating the level of cGMP in smooth muscle cells, in this pilot study we sought to analyse PDE5, NOTCH1 and NOTCH3 expression in TAA patients with Marfan’s Syndrome, BAV and TAV." (PMID 31434939, 2019). "We found that NOTCH3 expression was increased in Marfan syndrome and TAV samples while NOTCH1 was up-regulated only in Marfan syndrome aortas, suggesting that the defects of extracellular matrix structure present in this syndrome can affect NOTCH expression." (PMID 31434939, 2019). "Moreover, while NOTCH1 has does not have a defined role in pathogenesis of Marfan syndrome, NOTCH1 haploinsufficiency has been shown to exacerbate the aortic root dilatation in the Marfan syndrome mouse model." (PMID 36140728, 2022). "Marfan syndrome aortic root SMCs demonstrated a significant reduction in Notch3 expression with ERK blockade, whereas Notch1 and 2 did not significantly change." (PMID 31886938, 2020).
mesothelioma (3 papers, 2018 to 2020). A usually malignant and aggressive neoplasm of the mesothelium which is often associated with exposure to asbestos. "Specifically, elevated Notch-1 and reduced Notch-2 expression have been observed in mesothelioma cells compared to normal mesothelial cells (HM)." (PMID 33537296, 2020). "Noxa is inhibited by Notch1, which is activated and provides a pro-survival stimulus in mesothelioma, hence we investigated whether inhibition of Notch1 could be involved in the pro-apoptotic activity of metformin." (PMID 33537296, 2020). "It has been reported that activating the Notch1/Hes1 pathway could accelerate cell invasion, migration and proliferation through the PI3k/AKT/mTOR pathway in acute T lymphocyte leukaemia and mesothelioma." (PMID 31382985, 2019).
metabolic syndrome (3 papers, 2019 to 2021). A cluster of metabolic risk factors for CARDIOVASCULAR DISEASES and TYPE 2 DIABETES MELLITUS. "Finally, Notch1 gain of function mutations resulted in worsened insulin resistance and increased serum glucose levels, reminiscent of the phenotypes seen in patients with metabolic syndrome." (PMID 31615106, 2019). "Taken together, our results suggest that haploinsufficiency of Notch1 promotes fat accumulation and adipogenesis and provides a mechanistic link between Notch signaling and development of metabolic syndrome." (PMID 34408185, 2021). "It has been reported that low shear stress induces the downregulation of miRNA126-5p resulting in the upregulation of Dlk1 which, by inhibiting Notch1, hinders ECs proliferation required for the efficient renewal of the endothelium damaged by dyslipidemia." (PMID 31191522, 2019). "In contrast, a 2016 study reported that hepatocyte-specific deletion of Notch1 resulted in decreased insulin sensitivity and increased serum glucose, similar to what is seen in metabolic syndrome." (PMID 31615106, 2019).
myeloid leukemia (3 papers, 2011 to 2018). A clonal proliferation of myeloid cells and their precursors in the bone marrow, peripheral blood, and spleen. "These different outcomes of defective NOTCH1 signalling across myeloid leukaemias show the complexity of this signalling pathway." (PMID 25711903, 2015). "Activating mutations of NOTCH1 have been postulated to be restricted to T-ALL and are rare in myeloid leukaemias." (PMID 25711903, 2015).
neuroendocrine carcinoma (3 papers, 2017 to 2025). A malignant neuroendocrine neoplasm composed of cells containing secretory granules that stain positive for NSE and chromogranin. "NOTCH1 activation may be a therapeutic strategy to unleash antitumor immune responses in SCLC and other neuroendocrine cancers in which NOTCH1 is typically suppressed." (PMID 40627448, 2025).
oropharyngeal carcinoma (3 papers, 2020 to 2025). Carcinoma, predominantly squamous cell, arising from the epithelial cells of the oropharynx. "Genomic studies of NOTCH1 mutations in HPV-driven oropharyngeal cancers demonstrated a spectrum of mutations similar to that in HPV-negative HNSCCs that are presumably inactivating." (PMID 33322834, 2020). "The average frequency rate for NOTCH1 mutations in HPV-positive oropharyngeal cancers is 10%, which is roughly half of that in HPV-negative HNSCC." (PMID 33322834, 2020).
ovarian adenocarcinoma (3 papers, 2005 to 2016). An adenocarcinoma that arises from the ovary. "Transfection experiments with activated Notch 1 intracellular domain in A2780 ovarian adenocarcinoma cells indicated a proliferative advantage due to Notch 1 that is consistent with an impaired contact inhibition at confluence." (PMID 16136053, 2005). "We did not detect overexpression of Notch 1 mRNA in ovarian adenocarcinomas (median expression level relative to PBGD : 0.35), but a tendency towards decreased Notch 1 expression in comparison to ovarian adenomas (median : 0.705)." (PMID 16136053, 2005).
pancreatic adenocarcinoma (3 papers, 2019 to 2021). "Pathway enrichment analysis showed the enhancement of “pancreatic adenocarcinoma signaling”, where the Notch1-NF-κB-COX2 pathway was activated." (PMID 30987352, 2019). "Based on the GEPIA database, we observed that Notch1, CDK5, p35, and p39 were overexpressed in pancreatic adenocarcinoma (PAAD) samples." (PMID 33960694, 2021).
papilloma (3 papers, 2010 to 2021). A benign epithelial neoplasm that projects above the surrounding epithelial surface and consists of villous or arborescent outgrowths of fibrovascular stroma. "In line with the non-redundant roles of Notch1 and Notch2 in keratinocytes is the accelerated papilloma formation in double Notch1/2-deficient mice, suggesting that Notch2 cannot fully compensate for Notch1 loss." (PMID 21042537, 2010). "We sporadically (below 0.5%) found K14+ cells with recombined Notch1 loci hypothesizing that these cells could be the cell-of-origin for papilloma development." (PMID 21042537, 2010). "As papilloma development in Pdx1-Cre mice usually occurred in regions susceptible to grooming, scratching and wounding, we speculated that PDX1 expression may be induced in wounded skin triggering Cre-mediated KrasG12D activation and Notch1 ablation." (PMID 21042537, 2010).
Parkinson disease (3 papers, 2016 to 2024). A progressive degenerative disorder of the central nervous system characterized by loss of dopamine producing neurons in the substantia nigra and the presence of Lewy bodies in the substantia nigra and locus coeruleus. "Our findings identify Notch1 as a direct downstream target of Rbm24, implicating the Rbm24/Notch1 signaling axis in Parkinson-associated olfactory dysfunction." (PMID 39113792, 2024). "It should be noted that highly activated Notch-1 is associated with many neurodegenerative disorders such as Alzheimer's or Parkinson's diseases." (PMID 27655677, 2016).
preeclampsia (3 papers, 2013 to 2025). Preeclampsia is a hypertensive disorder of pregnancy that is characterized by new-onset hypertension with proteinuria presenting after 20 weeks of gestation, and depending on mild or severe forms may initially present with severe headache, visual disturbances, and hyperreflexia. "Notably, the F11R, NOTCH1, GRHL3, and CLDN14 genes were associated with preeclampsia-associated PTB." (PMID 40625359, 2025). "Hsa-miR-494-3p may influence the development of preeclampsia disease by affecting the expression of Notch-1." (PMID 38041082, 2023). "In the physiologic placenta, NOTCH1 expression is thought to be vital for placental angiogenesis, while defective NOTCH signaling is thought to contribute in the pathogenesis of preeclampsia." (PMID 23586024, 2013).